MIR184 (microRNA 184)
Synonyms: hsa-mir-184; EDICT; MIRN184; miR-184
Gene: MicroRNA gene on chromosome 15 (79,209,788 to 79,209,871, forward strand). Ensembl gene ENSG00000207695.
Gene Ontology:
Biological process: miRNA-mediated post-transcriptional gene silencing
Cellular component: RISC complex
Homologues: Orthologues: chimpanzee ptr-mir-184 (100% identical), macaque mml-mir-184 (98% identical), pig ssc-mir-184 (95% identical), dog MIR184 (80% identical), tropical clawed frog xtr-mir-184 (76% identical), zebrafish dre-mir-184-1 (76% identical), guinea pig MIR184 (74% identical), zebrafish dre-mir-184-2 (73% identical), rabbit MIR184 (71% identical), Drosophila melanogaster mir-184 (58% identical).
Diseases named in the same sentence as MIR184 in open-access papers:
MIR184 is named in the same sentence as 8 diseases in open-access papers, as found by Europe PMC text mining. Sharing a sentence is not in itself a finding about the gene and the disease. The quoted sentences say what the papers report.
keratoconus (4 papers, 2014 to 2026). A degenerative, structural disorder of the eye, characterized by a cone-shaped protrusion of the cornea. "Beyond these structural genes, a frameshift or missense mutation in MIR184, the gene for microRNA-184, causes a familial syndrome of early-onset anterior polar cataract and keratoconus (sometimes called the EDICT syndrome)." (PMID 41595486, 2026). "Mutations in the MIR184 gene were mostly confirmed in keratoconus in association with other abnormalities of the anterior segment." (PMID 35456395, 2022). "Mutations in MIR184 have been studied in patients with keratoconus." (PMID 35456395, 2022). "In cases of isolated keratoconus, mutations in MIR184 were reported to be rare." (PMID 35456395, 2022). "They concluded that mutations in the seed region of MIR184 are rare in patients with isolated keratoconus and may be more relevant to cases of keratoconus associated with other ocular abnormalities." (PMID 35456395, 2022). "However, using this approach in large extended pedigrees has led to the identification of two potential genes (MIR184 and DOCK9) associated with keratoconus." (PMID 25254113, 2014). "Even in typical KC cases without MIR184 mutations, there is growing evidence that global miRNA expression is perturbed in keratoconus." (PMID 41595486, 2026). "However, a study in 780 keratoconus patients could identify MIR184 variants in only 0.25% (two) patients indicating that variants in MIR184 gene may not account for isolated keratoconus." (PMID 25254113, 2014). "Family-based studies have led to the identification of MIR184 and DOCK9 genes in cases with familial keratoconus; however, the replication of locus identified in a specific keratoconus family in other families (even in homogeneous population) has been very limited." (PMID 25254113, 2014).
hearing loss (1 paper, 2024). "Examples of such genetic diseases include hearing loss associated with MIR96 mutations, eye disorders linked to MIR184 mutations, and skeletal dysplasia involving MIR140 mutations." (PMID 39457367, 2024).
myopia (1 paper, 2015). "In a similar context, various reports have subsequently highlighted an association between point mutations within the seed region of MIR184 and KC with/without other ocular abnormalities including cataract and myopia." (PMID 26380287, 2015).
MIR184 also shares sentences with these, for which no sentence is quoted: EDICT syndrome (1 paper); endothelial dystrophy (1); genetic diseases (1); pituitary tumor (1); skeletal dysplasia (1).